LDHA (lactate dehydrogenase A)
Diseases named in the same sentence as LDHA in open-access papers (continued):
Sharing a sentence is not in itself a finding about the gene and the disease.
thyroid cancer (14 papers, 2015 to 2025). "The study discovered that the tissues of several thyroid cancer cell lines and patients’ tumors had much higher levels of LDHA expression, which is frequently linked to tumor aggressiveness, the risk of metastases, and a poor prognosis." (PMID 40917751, 2025). "The aberrant expression and upregulation of LDHA are closely related to a variety of cancers and associated with poor prognosis of patients with cancers, including thyroid cancer." (PMID 34404767, 2021). "And it is reported that glycolysis-related proteins, such as LDHA, are associated with invasiveness and prognosis of thyroid cancer." (PMID 34563154, 2021). "In summary, we demonstrated that increased levels of total and phosphorylated forms of PKM2 and LDHA in malignant tissues represent a novel expressional signature with diagnostic potential for thyroid cancer." (PMID 25880801, 2015). "Furthermore, LDHA overexpression has been found in BRAF V600E-mutated thyroid cancer and inactivation of this protein can make cells more sensitive to radiation." (PMID 33382739, 2020). "We then used immunohistochemical analysis to evaluate the expression levels of SOX12, YBX1 and LDHA in thyroid cancer tissues with different expression levels of SOX12." (PMID 40593465, 2025). "LncRNA LINC00671 is inversely correlated with LDHA levels, and inhibition of its expression can increase LDHA content in thyroid cancer cells and promote glycolysis, growth, and lung metastasis both in vitro and in vivo." (PMID 39609317, 2024). "This increases the LDHA content in tumor cells and promotes glycolysis and proliferation of thyroid cancer." (PMID 37582735, 2023). "Y10 is the most reported phosphorylated site of LDHA, which is shown upregulated in thyroid cancer tissues as compared to goiter." (PMID 36407005, 2022). "The authors demonstrate that phosphorylation of LDHA occurs in an FGFR1-specific manner, which is an additional regulatory mechanism underlying the Warburg effect and lactate production in thyroid cancer cells." (PMID 36407005, 2022). "LDHA increases proliferation, invasion, and metastasis of thyroid cancer cells and helps thyroid cancer cells escape from immunity." (PMID 34404767, 2021). "Our research identified a novel STAT3/LINC00671/LDHA axis to regulate glycolysis, growth, and metastasis of thyroid cancer." (PMID 34404767, 2021). "STAT3/LINC00671/LDHA axis regulates thyroid cancer glycolysis, growth, and lung metastasis both in vitro and in vivo." (PMID 34404767, 2021). "Here, we identified a novel lncRNA LINC00671 negatively correlated with LDHA, downregulating LDHA expression and predicting good clinical outcome in thyroid cancer." (PMID 34404767, 2021). "Lactate dehydrogenase A (LDHA), a critical component of the glycolytic pathway, relates to the development of various cancers, including thyroid cancer." (PMID 34404767, 2021). "In this study we demonstrated that total and phosphorylated PKM2 and LDHA proteins are significantly up-regulated in thyroid cancer tissues as compared to goiter." (PMID 25880801, 2015). "With regards to our data, we found that in thyroid carcinoma tissues PKM2 is expressed more abundantly than LDHA." (PMID 25880801, 2015). "We further investigated whether SOX12 regulated the migration and invasion of thyroid cancer cells by regulating LDHA expression." (PMID 40593465, 2025). "The transcriptional regulation of LDHA by SOX12 encouraged us to determine whether LDHA was a functional downstream target of SOX12 during its promotion of thyroid cancer metastasis." (PMID 40593465, 2025). "LDHA was highly expressed in lung, kidney and thyroid cancer tissues." (PMID 38291366, 2024). "LDHA is reported to facilitate glycolysis, growth, and metastasis in thyroid cancer." (PMID 38764020, 2024). "For example, LDHA increases glycolysis and proliferation in thyroid cancer." (PMID 38764020, 2024).
thyroid cancer (continued). "Inhibition of LDHA or STAT3 or supplement of LINC00671 could be potential therapeutic strategies in thyroid cancer." (PMID 34404767, 2021). "LINC00671 or STAT3 activation may be useful for treatment of thyroid cancer with LDHA overexpression." (PMID 34404767, 2021). "Therefore, LDHA is considered as a promising target for thyroid cancer prevention and treatment." (PMID 34404767, 2021). "In thyroid cancer patients, LINC00671 expression is negatively correlated with LDHA and STAT3 expression." (PMID 34404767, 2021). "The majority of metabolism-related molecules, such as GLUT1 (glucose transporter 1), HK1 (hexokinase 1), LDH-A (lactate dehydrogenase A), GLS1 (glutaminase), and MCT1 (monocarboxylate transporter 1) are upregulated in different subtypes of thyroid carcinoma." (PMID 31947935, 2020). "In thyroid cancer, lncRNA LINC00671 is negatively correlated with LDHA levels." (PMID 37582735, 2023). "Moreover, in thyroid cancer samples, STAT3 or LINC00671 expression is negatively correlated with LDHA expression as well as increased tumor FDG uptake." (PMID 34404767, 2021). "In accordance with these findings we were able to show that thyroid carcinoma samples revealed not only significantly elevated levels of total PKM2 and LDHA compared to goiter or FA, but this expressional increase correlated directly with phosphorylated forms of both proteins." (PMID 25880801, 2015). "Phospho-PKM2 and Phospho-LDHA could be valuable tumour markers for thyroglobulin negative thyroid cancer." (PMID 25880801, 2015). "So far, FGFR1-mediated phosphorylation effects on LDHA and PKM2 have only been demonstrated in cell culture experiments without any relevance to human cancer tissue, especially thyroid carcinoma." (PMID 25880801, 2015).
oral squamous cell carcinoma (13 papers, 2019 to 2025). "LDHA was upregulated in oral squamous cell carcinoma and promoted cancer progression by enhancing glycolysis." (PMID 38990159, 2024). "A previous study reported that cisplatin treatment reduces LDHA expression in human oral squamous cell carcinoma cell lines, suggesting that changes in LDHA levels may add complexity to the interpretation of LDHB-mediated effects in this context." (PMID 40790017, 2025). "The LDHA gene expresses an enzyme that mediates metabolic plasticity in the bidirectional conversion of pyruvate and lactate, which favours the invasiveness and progression of oral squamous cell carcinoma." (PMID 34987583, 2021). "Despite LDHA exhibiting carcinogenesis in various cancers, its role in oral squamous cell carcinoma (OSCC) remains unclear." (PMID 31921691, 2019). "In oral squamous cell carcinoma (OSCC), lactate dehydrogenase A (LDHA) can facilitate glycolysis and epithelial-mesenchymal transition, thereby promoting the invasion and proliferation of OSCC cells." (PMID 33584825, 2021). "LDHA determination in saliva sample has been proposed for detection and monitoring of oral squamous cell carcinoma (OSCC), since the major source of salivary LDHA are the oral epithelium-shedding cells." (PMID 31737570, 2019).
clear cell renal cell carcinoma (12 papers, 2014 to 2026). "Through its facilitation of LDHA phosphorylation, FKBP10 enhances the advancement of clear cell renal cell carcinoma and controls susceptibility to HIF2α inhibition." (PMID 39968078, 2025). "IGF2BP1 participates in clear cell renal cell carcinoma (ccRCC) by recognizing sites on LDHA mRNA modified with m6A marks, increasing LDHA mRNA stability and accelerating aerobic glycolysis." (PMID 37055798, 2023). "The highly expressed IGF2BP1 directly binds to the m6A modification site on LDHA mRNA, thereby enhancing the stability of LDHA mRNA and promoting glycolysis and malignant phenotype of clear cell renal cell carcinoma." (PMID 37582735, 2023). "Our results indicate that LDHA up-regulation can be a predictor of poor prognosis in clear cell renal cell carcinoma." (PMID 24885701, 2014). "We also correlated the LDHA expression with overall survival, at mRNA level, in an independent data set of 170 clear cell renal cell carcinoma cases from The Cancer Genome Atlas databases." (PMID 24885701, 2014). "Additionally, FKBP10 promotes clear cell renal cell carcinoma progression and modulates HIF2α blockade sensitivity by facilitating LDHA phosphorylation." (PMID 41454479, 2026). "The objective of this study is to evaluate the potential significance of lactate dehydrogenase A (LDHA), assessed by immunohistochemical staining, as a prognostic marker in clear cell renal cell carcinoma in relation to clinicopathological features and clinical outcome." (PMID 24885701, 2014). "Moreover, LDHA expression shows significantly inverse correlation with both disease-free survival and overall survival in patients with clear cell renal cell carcinoma." (PMID 24885701, 2014). "Therefore, our study demonstrates that FKBP10 promotes clear cell renal cell carcinoma progression and regulates sensitivity to HIF2α blockade by facilitating LDHA phosphorylation, which may be exploited for anticancer therapy." (PMID 38233415, 2024). "Although oxidative phosphorylation was the preferred energy production process, cancer cells including clear cell renal carcinoma (ccRCC) usually acquired energy from glycolysis, and further studies proved that LDHA could also promote tumor progression through glycolysis." (PMID 37925501, 2023). "Similarly, the effect of LDHA on KICH is also not reported, while it has been found that LDHA was involved in clear cell renal cell carcinoma." (PMID 37925501, 2023).
lactic acidosis (12 papers, 2008 to 2025). Metabolic acidosis characterized by the accumulation of lactate in the body. "In addition, the pathogenesis of diabetic kidney disease (DKD) is associated with LDHA-mediated lactic acidosis, which leads to mitochondrial abnormalities and renal fibrosis in DKD patients." (PMID 39044840, 2024). "Further research has identified that local lactic acidosis, induced by enhanced lactate dehydrogenase A (LDHA) activity in diabetic patients, is a key driver in the progression of DKD." (PMID 40748976, 2025). "When oxidative respiration is not possible, mitochondrial pyruvate is converted to lactate via lactate dehydrogenase A (LDHA), and indeed, increased lactate levels and lactic acidosis are commonly seen in m.3243A>G patients." (PMID 36010669, 2022). "Inhibition of LDHA activity significantly improves renal fibrosis and functional damage, suggesting that local lactic acidosis may serve as a potential intervention target for DKD." (PMID 40748976, 2025). "Additionally, in the KKU-213A CCA cell line, which harbors numerous mtDNA SNVs, prior studies have shown that ALDH1A3 expression significantly rises under lactic acidosis (LA) conditions and correlates with LDHA expression." (PMID 40489465, 2025). "Lactic acidosis induced by the SIX1/LDHA axis in cancer cells also leads to NK cell dysfunction." (PMID 40165895, 2025). "Increased LDHA expression may result in lactic acidosis, a well-reported event in PAH." (PMID 32041182, 2020). "Lactate dehydrogenase-A (LDH-A) expression was needed to consume glucose and generate lactic acidosis that paralleled rapid proliferation." (PMID 24086675, 2013). "Notably, the elevated levels of LDHA in skeletal muscle have also been reported in cohorts of patients with PEO and mitochondrial encephalopathy lactic acidosis and stroke-like episodes syndrome (MELAS), suggesting implications for not only PD, but also mitochondrial diseases." (PMID 31843010, 2019).
myeloma (12 papers, 2016 to 2024). "The heatmap for OPM2 additionally contains LDHA (encoding lactate dehydrogenase A), which promotes growth and drug resistance of myeloma by virtue of lactate production." (PMID 35794249, 2022). "The expression of NEK2 and glycolysis-enhancing genes, such as hexokinase 2 (HK2), alpha-enolase (ENO1), and lactate dehydrogenase A (LDHA), was significantly increased in high-risk myeloma samples and positively correlated each other." (PMID 28086949, 2017). "This is mediated by hexokinase 2 (HK2), phosphofructokinase (PFK), pyruvate kinase M2 (PKM2) and lactate dehydrogenase A (LDHA) that are highly expressed in myeloma." (PMID 34768861, 2021). "miR-489 was reported to inhibit the growth of multiple myeloma by regulating the LDHA-mediated glycolytic metabolism." (PMID 34456629, 2021). "In addition to FOXM1, LDHA is upregulated in myeloma via HIF1A (hypoxia inducible factor 1 subunit alpha) and PPARGC1B (peroxisome proliferator-activated receptor gamma coactivator 1 beta)." (PMID 35794249, 2022). "Human myeloma cell lines (HMCLs) subjected to hypoxic conditions and thereafter treated with bortezomib, dexamethasone and melphalan were observed to have increased glucose metabolism, with and overexpression of LDHA and HIF-1α post-treatment." (PMID 35454812, 2022). "Additionally, HKII and lactate dehydrogenase A (LDHA) are found to be highly upregulated in relapsed MM patients compared to newly diagnosed myeloma patients, indicating increased glucose metabolism." (PMID 29662010, 2018). "Consistently, the expression of HK2, ENO1, LDHA, glucose transporter type 4 (Glut4), and monocarboxylate transporter 4 (MCT4) was downregulated in NEK2 silenced myeloma cells." (PMID 28086949, 2017). "Our findings further reveal that activated Akt and STAT3 pathways induce the upregulation of HIF1α and its downstream targets (LDHA and PDK1), leading to increased glycolysis in myeloma cells." (PMID 28345605, 2017). "KD of LDHA and HIF-1α was reported to restore sensitivity to a chemodrug on multiple myeloma cell lines." (PMID 27708237, 2016). "Reelin’s role in myeloma cell glycolysis was further supported by the clinical data from GSE24080 as high RELN-expressing patients also revealed high levels of HIF1α, PDK1, and LDHA expression." (PMID 28345605, 2017).
leukemia (11 papers, 2019 to 2025). A malignant (clonal) hematologic disorder, involving hematopoietic stem cells and characterized by the presence of primitive or atypical myeloid or lymphoid cells in the bone marrow and the blood. "Elevated level and activity of LDHA is observed in K562/MDR leukaemia cells, and oxamate (an LDHA inhibitor) not only inhibits glycolytic flux but also restores the sensitivity of K562/MDR cells to adriamycin by counteracting Akt/mTOR/c-Myc signaling." (PMID 40612109, 2025). "While the precise mechanism of LDHA inhibition through RNA suppression remains elusive, studies have demonstrated that LDHA gene knockout can delay leukemia progression." (PMID 40948941, 2025). "For instance, impairment of glycolysis by either pyruvate kinase M2 (PKM2) or lactate dehydrogenase-A (LDHA) deletion could markedly delay leukemia initiation in both CML and acute myeloid leukemia (AML) models." (PMID 31607919, 2019). "Furthermore, studies have shown that deletion of glycolysis enzymes pyruvate kinase isoform M2 (PKM2) and lactate dehydrogenase A (LDHA) delays leukemia progression, and the inhibition of glycolysis can significantly suppress AML cell proliferation and promote apoptosis." (PMID 38267416, 2024). "The Warburg effect occurs in leukemia with the help of enzymes such as pyruvate kinases M2 (PKM2), lactate dehydrogenase A (LDHA), pyruvate dehydrogenase kinase 1 (PDK1), and fibroblast growth factor receptor 1 (FGFR1)." (PMID 34659946, 2021). "The Warburg effect in leukemia has been attributed to specific enzymes such as PKM2, LDHA, and PDK1." (PMID 34659946, 2021). "JQ1 is able to restrain the glycolysis of leukemia cell lines by downregulating the rate-limiting enzymes of glycolysis, hexokinase 2, pyruvate kinase M2 (PKM2), and lactate dehydrogenase A. This effect is also mediated by the inhibitory effect of JQ1 on c-Myc, which enhances glycolysis." (PMID 37686632, 2023). "In leukemia, PKM2, LDHA, PDK1, and FGFR1 play an important role in establishing the Warburg effect." (PMID 34659946, 2021).
pancreatic ductal adenocarcinoma (11 papers, 2021 to 2026). An infiltrating adenocarcinoma that arises from the epithelial cells of the pancreas. "An in-depth study demonstrated an interaction between NUSAP1 and lactate dehydrogenase A (LDHA) in pancreatic ductal adenocarcinoma (PDAC)." (PMID 40535133, 2025). "Lysine lactylation of nucleolar and spindle-associated protein 1 (NUSAP1) by CBP/p300 in pancreatic ductal adenocarcinoma (PDAC) enhances its association with the LDHA promoter, hence increasing LDHA expression." (PMID 40755753, 2025). "In oncological studies, nucleolar- and spindle-associated protein 1-mediated lactylation, in conjunction with lactate dehydrogenase A, forms a positive feedback loop that promotes pancreatic ductal adenocarcinoma metastasis." (PMID 38291438, 2024). "Lactate dehydrogenase (LDHA), a metabolic enzyme that catalyzes the interconversion of lactate and pyruvate, is overexpressed in a wide variety of cancer types, including pancreatic ductal adenocarcinoma (PDAC)." (PMID 35982980, 2022).
brain tumor (10 papers, 2016 to 2025). "Staining of brain tumors isolated from mice after intracranial injection also verified that the expression of LDHA was significantly decreased in BrM3-shAKR1B10 group, compared with BrM3-shNC group." (PMID 37587486, 2023). "MB, CAIX, and LDHA expression in tissue microarrays of normal brain tissues, brain tumors, and cancer adjacent normal tissue." (PMID 33996536, 2021). "Despite the promising findings of a few studies presented here, the significance of LDHA in normal brain function and brain tumor initiation and progression is an area of research that is not receiving enough attention." (PMID 26269128, 2016). "The current knowledge of the role of LDHA in the brain and its potential as a therapeutic target for brain tumors will also be highlighted." (PMID 26269128, 2016). "The Warburg effect appears to be universal in tumors, including primary brain tumors, and LDHA (because of its involvement with this process) has been identified as a potential therapeutic target." (PMID 26269128, 2016). "Although a few studies of LDHA in brain tumors have shown promise, the extent of these studies is severely lacking." (PMID 26269128, 2016). "Here we investigate the expression of MB, and its correlation with the hypoxia markers carbonic anhydrase IX (CAIX) and lactate dehydrogenase A (LDHA), in human tissue microarrays of multiple organ tumors, brain tumors, and GBM tumors, and their respective cancer-adjacent normal tissues." (PMID 33996536, 2021). "Indeed, brain tumors, which overexpress LDHA, have elevated [1-13C]lactate production." (PMID 41030321, 2025). "Collectively, these studies suggest that LDHA‐targeted therapy could reduce tumor invasion and migration, which severely decreases a patient's chance of survival, especially in the context of primary brain tumor." (PMID 26269128, 2016). "Hypoxia markers (CAIX and LDHA) and MB protein expression was also investigated in a TMA of different brain tumors." (PMID 33996536, 2021). "We screened each group of TMA: multiple organ tumors (39 cases/43 cores), different brain tumors (40 cases/80 cores), and GBM tumors (40 cases/80 cores), each with its respective CANT for CAIX, LDHA, and MB protein expression." (PMID 33996536, 2021). "For example, similar expression levels of NDRG1, LDHA, MHCII molecules, interferon genes, GPM6A, C9, and SRGAP2 were discovered in different myeloid subpopulations, indicating the similar functional states in different brain tumors." (PMID 38094301, 2023). "Several studies have also demonstrated that LDHA has a role in tumor formation, maintenance and progression 27, 72, 75; however, there has not been adequate research into the use of LDHA as a prognostic marker for brain tumors." (PMID 26269128, 2016). "Even brain tumor stem cell (BTSC) lines that once had IDH mutations but lost their mutant IDH allele and no longer produced 2‐HG had silenced LDHA." (PMID 26269128, 2016).